MIR762 (microRNA 762)
Synonyms: hsa-mir-762
Gene: MicroRNA gene on chromosome 16 (30,893,903 to 30,893,985, forward strand). Ensembl gene ENSG00000211591.
Gene Ontology:
Biological process: cellular response to amino acid stimulus; response to muscle activity; response to oxygen levels; sensory perception of sound
Diseases named in the same sentence as MIR762 in open-access papers:
MIR762 is named in the same sentence as 1 disease in open-access papers, as found by Europe PMC text mining. Sharing a sentence is not in itself a finding about the gene and the disease.
MIR762 shares sentences with these, for which no sentence is quoted: tumor (1 paper).